CDC42 (cell division cycle 42)
Diseases named in the same sentence as CDC42 in open-access papers (continued):
Sharing a sentence is not in itself a finding about the gene and the disease.
tumor (continued). "Other shared hub proteins, including MAPK1, CDC42, and PIK3R1, are also involved in key signaling and regulatory pathways that support tumor progression." (PMID 41342186, 2025). "We also performed daily tail vein injection of a second CDC42 lead inhibitor (ARN25062) and ARN22089 and observed that both compounds stunted tumor growth and reduced vessel arborization in tumors grossly." (PMID 40950721, 2025). "Mechanistically, COA4 enhances tumor cell metastasis by upregulating mitochondrial OXPHOS and by interacting with CDC42 to activate its activity." (PMID 40936169, 2025). "The Wilcoxon rank sum test revealed significantly lower expression levels of CDC42 and ESR2 in tumor samples compared to normal tissues." (PMID 41246859, 2025). "We found that MC38 tumor cells inhibited motility of iNKT cells in vitro via a VCAM1 dependent manner, and that was restored by overexpression of CDC42 in iNKT cells." (PMID 38332012, 2024). "Together, our data indicate that tumor VCAM1 inhibits iNKT cell motility and activation via reducing CDC42 expression." (PMID 38332012, 2024). "Thus, we first examined whether the overexpression of IL-15 alters Cdc42 activity in tumor cells." (PMID 38637902, 2024). "It was previously shown that GRF2 suppresses the CDC42-dependent phosphorylation and activation of MLC2 (Myosin Light Chain 2) in cultured cell lines from different human tumor types." (PMID 37947653, 2023). "High expression of RAC1, RHOA, CDC42, and VEGFB were identified in metastatic subgroups, compared to primary tumor and normal lung epithelia clusters." (PMID 37202394, 2023). "CDC42 GTPases (RHOJ,CDC42, and RHOQ) are overexpressed in multipletumor types and activate pathways critical for tumor growth, angiogenesis,and metastasis." (PMID 37026468, 2023). "Cdc42, in conjunction with Rho A, regulates PTEN localization and activity at the cell membrane, which contributes to the ability of PTEN to act as a tumour suppressor." (PMID 37114375, 2023). "Previous studies indicate an important role for CDC42 in EMT-mediated migration and invasion of individual tumor cells." (PMID 37365287, 2023). "Here, we have presented additional effortsof our drug discoveryprogram targeting the CDC42 GTPase (RHOJ, CDC42, and RHOQ) proteins,which are overexpressed in multiple tumor types." (PMID 37026468, 2023). "In the case of CDC42, the TWF1 and SELT genes were identified as co-expressed in all three groups: healthy tissue, adjacent healthy tissue, and tumor tissue." (PMID 37365287, 2023). "Molecular mechanism study found that STARD14 may promote tumor progression via directly act on CSE1L, and associated with several multiple tumor-related signaling, including Wnt/ β - catenin signaling, PI3K / Akt signaling, Cdc42 signaling, and SAPK / JNK signaling." (PMID 37790851, 2023). "The results showed that increased CDC42, CDH2, ERBB2, JAG1, YAP1, and YWHAZ were found in the tumor tissues." (PMID 35340237, 2022). "These differential proteins were enriched in tumor-related pathways, including tumor growth, tumor invasion, immune response, metabolism, and signaling (RAC, FAK, CDC42, and RhoA) pathways." (PMID 35589723, 2022). "A recently characterized NSC derivative IODVA1 targets Rac and Cdc42, and significantly inhibits triple-negative breast cancer (TNBC) tumor growth in mice; however, this compound is effective only at μmol/L concentrations." (PMID 36861094, 2022). "AZA1 can effectively inhibit the activation of Cdc42 and Rac1, reduce the signal transduction of the PAK pathway, and inhibit tumor growth." (PMID 35154449, 2022). "To validate expression levels of the CCNB1/CDC42/MAPK7/CD44 gene signatures in GBM, we explored the HPA database for IHC to compare gene expression levels between GBM tumor tissues and normal samples." (PMID 35008426, 2022). "This molecule selectively targets CDC42 GTPases, inhibits MAPK and S6 signaling, and inhibits tumor growth and tumor angiogenesis." (PMID 35385746, 2022).
tumor (continued). "To verify a functional interaction between CD99 and CDC42 we performed RNAi against tumour cell CD99 and CDC42, individually and in combination." (PMID 34374417, 2021). "In the context of chronic lymphocytic leukemia, CDC42 upregulation, together with downregulation of RAC1 and RHOA, upon direct contact with tumor cells, impairs migration of T cells and therefore immunosurveillance." (PMID 33406731, 2021). "The present study found that Rac1/Cdc42 was highly expressed in RMS, and the IHC results showed that the protein expression was homogeneous in all tumor regions." (PMID 34221974, 2021). "Increasing studies showed that both the Rho family and MMP family, including Rac1/2/3, CDC42, RhoA, RhoC, MMP2, and MMP9, are highly expressed in a variety of tumor tissues and are directly correlated with tumor migration and invasion." (PMID 33377649, 2020). "Increased rigidity in the tumor stroma favors EGFR activity and results in the calcium-dependent regulation of Cdc42 small GTPase activity in tumor cells." (PMID 32546182, 2020). "In parallel, in accordance to previous reports that CD44 regulates Rho-family of GTPases to promote tumor progression, we show that SRGN promoted cytoskeleton reorganization via inducing Rac1 and CDC42 activation." (PMID 31898491, 2020). "For example, IQGAP1 can stabilise Cdc42 in its GTP-bound form, thereby increasing active Cdc42.18,19 High levels of IQGAP1 are observed in various tumours." (PMID 32632148, 2020). "The majority of these studies attributed the tumor-suppressor role of DLC1 to its RhoGAP domain, which inhibits the small GTPases RHOA/B/C and CDC42." (PMID 32214200, 2020). "Another important aspect of the implication of Cdc42 in the malignancy of GBM is the interaction between GBM cells and other cells in the tumor environment, specifically pericytes." (PMID 32089990, 2020). "Two key proteins in cell physiology—CDC42 and EGFR—seem to be central to these pathways, suggesting their relevance for tumor progression to stage 3." (PMID 31945087, 2020). "This suggests a dual role of StarD13; as 1- a tumor suppressor which attenuates RhoA (hence Raf-1/MEK/ERK proliferation and survival pathway) as well as 2- an invasion suppressor, which inhibits Cdc42." (PMID 32900380, 2020). "KU treatment downregulated the epithelial-mesenchymal markers Twist, Snail, and Slug and the metastasis-related genes CAPN1, CDC42, CFL1, IGF1, WASF1, and WASL in cells and tumor tissues." (PMID 30390003, 2018). "The interactions of Rage and its ligands have been reported to promote tumor progression by activating MAPK, NF-κB, PI3K/AKT, and cdc42 pathways." (PMID 29445087, 2018). "Stably expressing MEC-17 cells, which showed asthenic tumour metastatic ability, exhibited suppression of EMT, redistribution of cell polarization, higher cdc42 activity, and downregulation of Rho-GAP, ARHGAP21." (PMID 30504808, 2018). "Tumor migration and invasion are strictly regulated by actin cytoskeleton modulated by Rho family of small GTPases, including RAC1, Cdc42, and RhoA in space timely." (PMID 29802377, 2018). "To further study the oncogenic link between the up-regulation of CDC42 and subsequent silencing of CACNA2D2 in vivo, we further characterized the tumor xenografts generated by CDC42 for CDC42 and CACNA2D2 expression." (PMID 28460460, 2017). "Consist with the previous researches, our data demonstrated that inhibition of REPS2 would activate RalBP1/RAC1/CDC42, increase MMP2/9, thus promote tumor invasion and metastasis." (PMID 27120794, 2016). "The small Rho GTPases Rac1, RhoA and Cdc42, are key mediators in the Wnt/PCP pathway and important contributors to tumor migration and invasion." (PMID 26689985, 2016). "To definitively address this issue, we will need to knock out CDC42-v2-specific exon, exon 6B, using gene targeting technology such as CRISPR/Cas9 system and then examine the effects on tumor cell behaviors." (PMID 26336992, 2015).
tumor (continued). "CHD1L can contribute to tumor cell migration, invasion, and metastasis by increasing cell motility and inducing filopodia formation and EMT via ARHGEF9-mediated Cdc42 activation in HCC." (PMID 26599012, 2015). "While both GSDMB isoforms promote cell motility and invasion through activation of the Rho-GTPases Rac-1 and Cdc-42 in vitro, their analysis in xenograft mouse models showed that only GSDMB-2 increases tumor growth and metastasis." (PMID 24675552, 2014). "Here we show that the tumour suppressor DLC2, a GAP (GTPase-activating protein) for Cdc42, regulates microtubule growth and cortical actin polarization, and, thereby, coordinates spindle positioning and junctional integrity." (PMID 25518808, 2014). "Cdc42 knockdown and TMX treatment also showed modest effects on tumour volume as measured after 60 days of tumour growth." (PMID 23606532, 2013). "In animals transplanted with Cdc42 knockdown MDA-MB 231 cells, the average size of the tumour mass at 60 days after engraftment was only ∼20% the size of tumours generated from cells transduced with scrambled shRNA constructs." (PMID 23606532, 2013). "The smallest tumours were found in mice transplanted with Cdc42 knockdown cells and treated with TMX, with 5/6 tumours being smaller than any of the tumours found in any other experimental group (p < 0.05)." (PMID 23606532, 2013). "Our results demonstrate that lipid agonist-induced tumor cell invasion requires MT1-MMP, and its signaling occurs via LPA1, S1P1, Rac1, and Cdc42." (PMID 17156449, 2006). "In contrast, expression of Rac1 Cdc42, Rho-GDI and ERK2 in both grade I and grade III tumours was similar to that of MCF-7 cells." (PMID 12237774, 2002). "To determine whether COA4 regulates tumor cell migration through CDC42, we assessed the impact of altered COA4 expression on CDC42 protein levels and activity." (PMID 40936169, 2025). "Although Cdc42 expression remains unchanged compared to non-tumor tissue, we have found that its activity is directly correlated to reduced expression of FARP1, a guanine nucleotide-exchange factor (GEF), that activates Cdc42." (PMID 40666287, 2025). "Interestingly, genes with oncogenic potential, including CDC42, CDC14B, STK40, BRD3, CPNE1, and MCM3, were downregulated, whereas tumor inhibitors, including CDKN2C, CASP7, and CDKN1B, were upregulated by RBM15 depletion." (PMID 38825643, 2024). "Rac1 and Cdc42 activate PAK2, facilitating cytoskeletal dynamics and tumor progression." (PMID 39769207, 2024). "In order to investigate and compare the co-expression of adhesion molecules (CDC42, TAGLN, and GSN) in cancerous and healthy samples, 100 co-expressed genes were retrieved from GEPIA2 using data from TCGA COAD tumor samples, TCGA adjacent normal tissue samples, and GTEx healthy colon samples." (PMID 37365287, 2023). "Pharmacodynamics study performed by estimating the transcript levels of Rac1, Cdc42, HIF-1α, β-catenin and DDX3 in the tumor tissue reveled a significant downregulation of these important metastasis markers in the combination group as compared to the drug alone group." (PMID 37024613, 2023). "Considering we had proved that CEMIP activated CDC42/MAPK pathway, and it was reported that MAPK signaling was a key regulator of epithelial-mesenchymal transition (EMT) and tumor metastasis, we deduced that CEMIP promoted CRC metastasis via MAPK signaling-induced EMT." (PMID 36849460, 2023). "Given that ARHGEF37 is associated with EC adherence and trans-endothelial migration via regulating Cdc42 activity, we speculated that a Cdc42 inhibitor would be potential therapeutic agent for ARHGEF37-mediated tumor cell invasion." (PMID 35869555, 2022). "Importantly, tumor invasion-related proteins and pathways represented by RAC, FAK, CDC42, and RhoA signaling were enriched only in the DM group, demonstrating unique characteristics of metastatic CRC." (PMID 35589723, 2022).
tumor (continued). "Cdc42 is generally upregulated and involved in the activation of cell signaling pathways, including PAK and N-WASP, which are closely related to the malignant proliferation of tumor cells." (PMID 35154449, 2022). "In addition, RAC and CDC42 are able to inhibit cell cycle arrest in HCC via PAK5 and thereby facilitate tumor growth cells." (PMID 36348464, 2022). "The high CDC42 cargo in CRC‐EVs was transported into macrophages, where it acquired its GTP‐bound active state and subsequently, mediated NOD1 activation, triggering the inflammatory response to promote tumour cell migration." (PMID 36068649, 2022). "Meanwhile, in the remaining 4 cases (Case No. 4, 9, 21, 32), Rac/Cdc42 activity was reversed (normal mucosa versus tumor area = 1: 0.85)." (PMID 35110666, 2022). "In conclusion, this study suggests that miR-375-3p functions as a tumor suppressor which could inhibit the progression of HCC via targeting YWHAZ and CDC42." (PMID 35340237, 2022). "CDC42 and RHOJ are both known to have specific roles in tumor angiogenesis." (PMID 35385746, 2022). "Furthermore, palladin can control the activity of Cdc42 and increase the formation of adhesive membrane protrusions, called invadopodia, that can remodel ECM and promote tumour development in vivo." (PMID 33573141, 2021). "Western blot analysis of tumor lysates shows that Rac1, Cdc42, or RhoA protein levels were not substantially decreased as a consequence of R-ketorolac treatment in vivo or after 5 days of treatment in cell culture." (PMID 33413202, 2021). "Additionally, a lung cancer xenograft mouse model showed reduced tumour growth after treatment with ZCL367 and cell lines had reduced Cdc42-mediated filopodia formation." (PMID 34100887, 2021). "The documented pro- and anti-tumour activity of CD99 is mirrored by both positive and negative roles for CDC42 in tumour progression." (PMID 34374417, 2021). "Bioinformatic analyses predicted that APEX1 might interact with cell division cycle 42 (CDC42) and son of sevenless homolog 1 (SOS1), which are involved in tumor metastasis." (PMID 33946672, 2021). "Moreover, when E-cadherin expression switches to P-cadherin, further cytosolic translocation of p120 occurs leading to induction of tumor cell migration through activation of RAC1 and CDC42, tumor anchorage-independence and increased tumor growth in vivo." (PMID 33076339, 2020). "Moreover, we also observed that H2 treatment induced obvious inhibitions in the expression levels of CDC42 and CD47 in mice tumor tissues, as well as reinforced macrophage-mediated phagocytosis in A549 and H1975 cells." (PMID 32314789, 2020). "There is evidence to suggest that Cdc42 is involved in both the formation of invadopodia structures as well as the production and/or activation of MMPs responsible for the ECM digestion necessary for tumor cell invasion." (PMID 31817718, 2019). "In previous studies, we established the tumor suppressor StarD13 (steroidogenic acute regulatory protein)-related lipid transfer domain 13) as a GTPase-activating protein (GAP) that specifically inhibits RhoA and Cdc42 in GBM cells and other tumor models." (PMID 31698752, 2019). "ATX secreted from tumor and stromal cells induces LPA, which enhances NF-κB expression via the PKC or AKT pathway, induces ATF-2 via the Rho-CDC42-p38 MAPK pathway, and activates STAT3 and STAT5, which induces the synthesis of inflammatory cytokines, chemokines, and COX-2." (PMID 31035435, 2019). "In addition, overexpression of MEC-17 inhibited tumour metastasis, suppressed EMT, and disturbed cell polarization through cdc42 activation resulting from decreased expression of Rho-GAP, ARHGAP21." (PMID 30504808, 2018). "Such a regulatory role of uPARAP in small RhoGTPase activation was in agreement with previous studies, which reported that uPARAP regulates tumor cell mobility (MCF7 and MDA-MB231) induced by urokinase (uPA) and growth factors via the regulation of Cdc42 and Rac1 activation." (PMID 30518756, 2018).
tumor (continued). "Indeed, there is a significant increase in RhoC, Cdc42 and MYL9 expression levels in metastasis versus primary tumours, indicating that drivers of actomyosin contractility are selected during HCC metastatic dissemination." (PMID 27941881, 2017). "As the control, deletion of Cdc42 alone did not result in any tumor formation over 70 weeks post Ad-Cre treatment." (PMID 28871124, 2017). "The statistical correlation between CDC42 and CACNA2D2 in the tumor samples was also investigated." (PMID 28460460, 2017). "In the CDC42-wt1 group, CDC42 expression was comparable to that of the parental cells and subsequently, no delay in tumor formation was observed." (PMID 28460460, 2017). "Strong co-staining of both proteins from sequential sections could be detected in tumor samples with high CD47 expression, while minimal staining of Cdc42 was detected in those with low CD47 expression." (PMID 27411490, 2016). "These researches suggest that signals from REPS2 might suppress tumor growth and metastasis through RalBP1/RAC1/CDC42 signaling pathway." (PMID 27120794, 2016). "The expression of CDC42-v2 was lower in the malignant tissues than in the normal tissues, while the differences in the abundance of CDC42-v1between normal and tumor tissues were not statistically significant." (PMID 26336992, 2015). "DLC1 (Deleted in Liver Cancer 1) gene encodes a RhoGTPase-activating protein (RhoGAP), which exerts most of its tumor suppressor functions through suppression of small Rho GTPases proteins RhoA, RhoB, RhoC and to some degree Cdc42, but not Rac." (PMID 24683532, 2014). "Here we demonstrate that the tumour suppressor DLC2, a negative regulator of Cdc42, and the interacting kinesin Kif1B coordinate cell junction maintenance and planar spindle positioning by regulating microtubule growth and crosstalk with the actin cytoskeleton." (PMID 25518808, 2014). "Moreover, Cdc42-mediated inhibition of c-Cbl function was apparently so effective that expression of shRNA for c-Cbl in MDA-MB 231 cells expressing scrambled shRNA constructs did not cause any further increases in rate of tumour growth or decreases in time to death." (PMID 23606532, 2013). "Western blotting of isolated tumor tissue indicated that AZA197 treatment does not change Cdc42 and total PAK and ERK expression." (PMID 24279335, 2013). "When mice were transplanted with cells that co-expressed shRNAs for Cdc42 and c-Cbl the rate of tumour growth and the time of survival were indistinguishable from mice transplanted with cells expressing scrambled shRNA for Cdc42." (PMID 23606532, 2013). "The RAC1, CDC42, FAS, and PDGFR signaling pathways all appear in the top 15 pathways with altered consistency (yet appear lower in our list according to activity) and have been shown to play a large role in GBM tumor formation." (PMID 21542931, 2011). "Summarising the data, a good correlation with clinically established tumour markers was observed with RhoA-like proteins but not with Rac1 and Cdc42." (PMID 12237774, 2002). "Paired analysis of matched normal‐tumor samples confirmed this pattern for MAPK14 but not CDC42." (PMID 41246859, 2025). "Variations within genes of the MAPK signaling pathway in TECs, such as amplifications in CDC42, HSPB1, NRAS, and deletions in AKT1, MAPK1, might reveal their significance in HCC, possibly related to their roles in tumor growth and progression, particularly in signaling pathways." (PMID 39484208, 2024). "Essential genes in angiogenesis and invasion, VEGFA, SPAG9, and CDC42, were distinctly upregulated in H3F3B+ tumor cells and clustered in the angiogenesis and invasion pathways, suggesting that H3F3B+ tumor cells may exert angiogenic and invasive effects." (PMID 37430270, 2023).